FGF18 (fibroblast growth factor 18)
Diseases named in the same sentence as FGF18 in open-access papers (continued):
Sharing a sentence is not in itself a finding about the gene and the disease.
cleft palate (3 papers, 2016 to 2025). Cleft palate is a fissure type embryopathy that affects the soft and hard palate to varying degrees. "Our findings reveal that Wnt1-Cre;pMes-Fgf18 mice exhibited cleft palate, mandibular deformation, and tongue malposition, indicating that a precise equilibrium of endogenous FGF18 signaling is essential for normal craniofacial development." (PMID 38694818, 2024). "The results showed that overexpression of Fgf18 leads to craniofacial abnormalities in mice similar to the Pierre Robin sequence in humans, including abnormal tongue morphology, micrognathia, and cleft palate." (PMID 38694818, 2024). "Previous research has shown that conditional knockout of Fgf18 in CNCCs results in mice with cleft palate and micrognathism." (PMID 38694818, 2024). "Thus, further investigation of the role and molecular mechanisms involving Fgf18 in palate development will directly improve our understanding of the genetic basis and molecular mechanisms of cleft palate pathogenesis in humans." (PMID 26745863, 2016). "Our results demonstrated that Wnt1-Cre;pMes-Fgf18 mice exhibited the characteristic features of the PRS, such as cleft palate, abnormal tongue placement, micrognathia, and skull malformations." (PMID 38694818, 2024). "Interestingly, mice lacking Fgf18 function exhibit high penetrance of cleft palate." (PMID 26745863, 2016).
idiopathic pulmonary fibrosis (3 papers, 2017 to 2022). Idiopathic pulmonary fibrosis (IPF) is a nonneoplastic pulmonary disease that is characterized by the formation of scar tissue within the lungs in the absence of any known cause. "The fibroblast growth factor 9 (FGF9) and 18 (FGF18) also inhibit myofibroblast differentiation in idiopathic pulmonary fibrosis and their biological effects are partially driven by FGFR344." (PMID 28717200, 2017). "In contrast, FGF9 is elevated in tissue samples from patients with mild to severe idiopathic pulmonary fibrosis (IPF), and FGF9 and FGF18 both contribute to the development of IPF in tissue culture." (PMID 35675358, 2022).
non-small cell lung carcinoma (3 papers, 2022 to 2023). A group of at least three distinct histological types of lung cancer, including non-small cell squamous cell carcinoma, adenocarcinoma, and large cell carcinoma. "Furthermore, our research group recently found that HDAC7 increased SNAIL protein levels by regulating fibroblast growth factor 18 (FGF18) in non-small cell lung cancer." (PMID 35595735, 2022).
osteosarcoma (3 papers, 2021 to 2025). A usually aggressive malignant bone-forming mesenchymal neoplasm, predominantly affecting adolescents and young adults. "In a human osteosarcoma cell line, expression of FGF18 and BMP4 followed the same pattern as in the RNASeq data from SW1353 chondrosarcoma cells." (PMID 39963339, 2025).
clear cell renal cell cancer (2 papers, 2020 to 2023). "In gastroesophageal adenocarcinoma, in contrast, as well as in clear cell renal cell cancer, high FGF18 expression was found to be correlated with longer patient survival." (PMID 37340889, 2023). "However, there is still little information on the biological role of FGF18 on clear cell renal cell carcinoma (ccRCC), which is of interest in investigating the biological functions of FGF18 in ccRCC." (PMID 33117668, 2020).
colorectal adenoma (2 papers, 2016 to 2023). An adenoma that arises from the colon or rectum. "In conclusion, the CD44 marker on the surface of human colorectal adenoma cells as well as ERK can be mediated by FGF18 signaling, and Wnt can mediate FGF18 signaling activity." (PMID 37228502, 2023).
colorectal tumors (2 papers, 2010 to 2023). "However, FGFR3-IIIc not only exclusively bind FGF18, but also FGFs 1, 2, 4, 8 and 9, among which FGF9 is expressed in colorectal tumour cells (data not shown)." (PMID 20234367, 2010).
liver cancer (2 papers, 2021 to 2023). An epithelial or non-epithelial malignant neoplasm that arises from the liver. "In addition, Christine’s team showed that serum starvation induced apoptosis in HepG2 or Hep3B human liver cancer cells, which was reversed by the addition of human recombinant FGF18 protein." (PMID 37228502, 2023).
Obesity (2 papers, 2023 to 2025). Accumulation of substantial excess body fat. "In addition, obesity is established risk factors of CRC, through DNA methylation spectrum(Illumina InfiniumHumanMethylation450 BeadChip) epigenetic changes, estimate the FGF18 was associated with a significant CRC, May be an important intermediate biomarker for obesity and CRC." (PMID 37228502, 2023).
tear (2 papers, 2022 to 2025). "Next, 1D was administered in two doses intra-articularly (IA), in a post-traumatic medial meniscal tear (MMT, Lewis rats) model, and compared to sham, vehicle, and a positive control consisting of fibroblast growth factor 18 (FGF18) administration." (PMID 36552848, 2022).
abdominal aortic aneurysm (1 paper, 2022). Enlargement and ballooning of the vessel that supplies arterial blood to the abdomen, pelvis and legs. "We performed cellular and animal experiments to investigate the simultaneous function and mechanism of fibroblast growth factor 18 and integrin β1 in the biological repair of abdominal aortic aneurysms." (PMID 36115958, 2022). "Fibroblast growth factor 18 + integrin β1 improved the biological repair of abdominal aortic aneurysms in rats by increasing the expression of elastic proteins, improving the migratory and proliferative abilities of endothelial and smooth muscle cells, and improving aortic remodeling." (PMID 36115958, 2022).
achondroplasia (1 paper, 2019). Achondroplasia is the most common form of chondrodysplasia, characterized by rhizomelia, exaggerated lumbar lordosis, brachydactyly, and macrocephaly with frontal bossing and midface hypoplasia. "Aside from this, a missense mutation leading to a constantly active FGF receptor 3 (FGFR3), the authentic receptor for FGF18, was discovered to be the cause of the genetic short limb dwarfism, achondroplasia (ACH)." (PMID 31614494, 2019).
aneurysm (1 paper, 2022). Bulging or ballooning in an area of an artery secondary to arterial wall weakening. "The overall structure of the aortic wall in the AAA + LV-Itgβ1 + FGF18 group was relatively intact, and the elastic fibers were continuous, indicating that FGF18 + Itgβ1 can effectively promote the biological repair of aneurysm walls." (PMID 36115958, 2022).
aortic aneurysm (1 paper, 2022). A ruptured aneurysm located in the wall of the proximal portion of the descending aorta proceeding from the arch of the aorta. "Moreover, animal experiments showed that fibroblast growth factor 18 + integrin β1 could enhance the aortic integrity to withstand stretch of aortic aneurysm tissue." (PMID 36115958, 2022).
bladder cancer (1 paper, 2023). "In genome-wide expression analysis of bladder cancer cells treated with demethylating agents 5-aza-2’-cytidine and zebularine, FGF18 expression was downregulated in eight bladder cancer cell lines." (PMID 37228502, 2023). "Thus, FGF18 expression status in bladder cancer cell lines is downregulated by methylation of CpG residues located near the gene promoter region, with consequent impact on bladder cancer progression." (PMID 37228502, 2023).
bronchopulmonary dysplasia (1 paper, 2024). Bronchopulmonary dysplasia is a chronic respiratory disease that results from complications related to lung injury during the treatment of infant acute respiratory distress syndrome in low-birth-weight premature infants or from abnormal lung development in older infants. "Interestingly, previous findings identified FGF18 as a likely important player in the control of alveolar angiogenesis, an event that is an absolute requirement for alveolarization and is compromised in bronchopulmonary dysplasia." (PMID 38419044, 2024).
cartilage disease (1 paper, 2022). Softening and degeneration of the CARTILAGE. "Considering the structural homology of FGF‐18 and FGF‐8, understanding the role of FGF‐18 in cartilage diseases may provide some instructions for us to better understand FGF‐8." (PMID 35001536, 2022). "The difference between FGF‐18 and FGF‐8 in the progression of cartilage disease suggests that the FGF‐8 family has a dual role in the progression of cartilage disease, which may contribute to our complete understanding of the molecular mechanism of FGF‐8 in cartilage diseases." (PMID 35001536, 2022).
cervical cancer (1 paper, 2023). A primary or metastatic malignant neoplasm involving the cervix. "FGF18 may play an important role in guiding platinum-based therapy of cervical cancer." (PMID 37228502, 2023). "By gene analysis of 14 cervical cancer cell lines selected from the GDSC (Genomics of Cancer Drug Sensitivity) database, FGF18 significantly reduced the resistance of patients to cisplatin." (PMID 37228502, 2023).
Cognitive impairment (1 paper, 2025). Abnormal cognition is characterized by deficits in thinking, reasoning, or remembering. "FGF18 improves streptozocin-induced cognitive impairment, reduces Aβ accumulation, and attenuates neuronal damage such as nuclear pyknosis and apoptosis in rat brain." (PMID 39876880, 2025).
craniosynostosis (1 paper, 2022). Craniosynostosis is defined as the premature fusion of one or more cranial sutures leading to secondary distortion of skull shape resulting in skull deformities with a variable presentation. "Also, the genetic knockdown of FGF10 is related to skeletal phenotypes such as craniosynostosis in a mouse model, and FGF18 is expressed during osteoblast differentiation." (PMID 35980984, 2022).
dysplasia (1 paper, 2024). A usually neoplastic transformation of the cell, associated with altered architectural tissue patterns. "Previous studies have demonstrated that mice with deficiency in Fgf18 exhibit severe craniofacial dysplasia." (PMID 38694818, 2024).
ependymoma (1 paper, 2023). A WHO grade II, slow growing tumor of children and young adults, usually located intraventricularly. "In pediatric ependymoma studies, FGF18 was predicted to be an ependymoma-associated gene and associated with cell cycle by methylation and expression microarray data analysis." (PMID 37228502, 2023).
esophagogastric junction adenocarcinoma (1 paper, 2023). "In 2019, Austrian scientist Gerd conducted a preliminary analysis of FGF18 mRNA expression data of 87 patients with esophagogastric junction adenocarcinoma(AEG) in the Cancer Genome Atlas (TCGA) database, predicting that FGF18 has a high level of expression in AEG." (PMID 37228502, 2023).
facial clefting (1 paper, 2019). "FGF18 polymorphisms are associated with facial clefting, FGFR3 mutations cause skeletal dysplasias 35, and Fgf18 deleted mice have delayed chondrocyte differentiation." (PMID 31400222, 2019).
Hypertension (1 paper, 2022). The presence of chronic increased pressure in the systemic arterial system. "Interestingly, rs8109113 in the FGF22 gene was associated with both hypertension and height, and 17 SNPs in FGF10, FGF18, and FGF2 were associated with both osteoporosis and height." (PMID 35980984, 2022). "Similarly, the FGF2, FGF4, FGF10, FGF18, and FGF22 genes, which showed interactions with the FGFRL1 gene, were associated with height, hypertension, and osteoporosis." (PMID 35980984, 2022). "The FGF10, FGF18, FGF2, FGF4, and FGF22 genes, which interact with FGFRL1, were correlated with height, hypertension, and osteoporosis." (PMID 35980984, 2022).
hypertrophic cardiomyopathy (1 paper, 2023). A condition in which the myocardium is hypertrophied without an obvious cause. "To test our hypothesis that FYN plays a protective role in hypertrophic cardiomyopathy in Fgf18-CKO mice, we used AAV9 vectors carrying FYN under the control of the murine cTNT core promoter (AAV9-cTNT-FYN)." (PMID 36871047, 2023).
intestinal obstruction (1 paper, 2022). Blockage of the normal flow of the intestinal contents within the bowel. "All the deaths were caused by intestinal obstructions (one patient in each of the AAA, AAA + FGF18, and AAA + FGF18 + LV-Itgβ1 groups)." (PMID 36115958, 2022).
lung carcinoids (1 paper, 2023). "The BLAST program searches for human EST computer expression analysis derived from FGF18 mRNA and predicts that FGF18 mRNA is expressed in lung carcinoids." (PMID 37228502, 2023).
lung disease (1 paper, 2023). "The role of FGF18 in lung mesenchymal cell migration is not yet fully determined, however, it was demonstrated that FGF18 mediates migration in several adult lung disease." (PMID 37701781, 2023).
lymph node metastasis (1 paper, 2022). "In addition, the NSCLC patients with deep tumor invasion and/or larger tumors (T3–T4), high stages (stage III–IV), and lymph node metastasis (N1–N3) had higher FGF18 expression." (PMID 35277183, 2022).
myeloma (1 paper, 2010). "The five remaining genes (NRG2, Wnt4, Wnt11, Wnt16 and FGF18) were considered as a "myeloma MGF" although they were not statistically significantly overexpressed in MMC compared to environment cell populations." (PMID 20465808, 2010).
Myocardial fibrosis (1 paper, 2023). "Furthermore, picrosirius red staining showed that myocardial fibrosis and hydroxyproline content were exacerbated in the hearts of Fgf18+/−KO mice compared with those from WT controls after TAC." (PMID 36871047, 2023). "FYN overexpression partially protected Fgf18-CKO mice from hypertrophy, as well as cardiac function, myocardial fibrosis, and hydroxyproline content." (PMID 36871047, 2023).
myxoid liposarcoma (1 paper, 2015). A liposarcoma characterized by the presence of round non-lipogenic primitive mesenchymal cells and small signet ring lipoblasts within a myxoid stoma with a branching vascular pattern. "Several FGFs are described to promote neoangiogenesis, among them FGF2 but also FGF5 and FGF18, for which an overexpression in myxoid liposarcomas was detected in this study." (PMID 26036639, 2015).
omphalocele (1 paper, 2020). Omphalocele is an embryopathy classified in the group of abdominal celosomias and is characterized by a large hernia of the abdominal wall, centered on the umbilical cord, in which the protruding viscera are protected by a sac. "This, combined with the secondary VW defects or the kyphosis caused by the loss of Fgf18, causes the high rates of omphalocele that we observe in triple mutants." (PMID 32907848, 2020). "In Cited1Cre;Fgf8f/+;Fgf17Δ/Δ;Fgf18f/Δ embryos, the omphalocele frequency was similar to that observed in TCre;Fgf8f/+;Fgf17Δ/Δ;Fgf18f/Δ embryos, suggesting the requirement for Fgf18 in VW closure is in the somites." (PMID 32907848, 2020). "Consistent with the hypothesis that omphalocele is multifactorial in origin, we find that Fgf8 and Fgf17 are needed in the PSM whereas Fgf18 is required in the somites." (PMID 32907848, 2020).
Osteochondroma (1 paper, 2021). A common, benign cartiliginous neoplasm arising from the metaphysis of bone. "Inducible deletion of FGFR3 in adult mice resulted in endochondromas and osteochondromas, whereas global deletion of FGFR3 and one of its ligands, FGF18, led to aberrant chondrocyte proliferation in growth plates." (PMID 34625577, 2021).
osteoporosis (1 paper, 2022). A condition of reduced bone mass, with decreased cortical thickness and a decrease in the number and size of the trabeculae of cancellous bone (but normal chemical composition), resulting in increased fracture incidence. "Furthermore, several SNPs in FGF18 were associated with osteoporosis." (PMID 35980984, 2022).
pleomorphic liposarcoma (1 paper, 2023). Pleomorphic liposarcoma (PLS), the rarest subtype of liposarcoma (LS), is an aggressive, fast growing tumor located usually in the deep soft tissues of the lower and upper extremities. "By RT-PCR, FGF18 gene was detected in SS cell lines and SS tumor tissues, and the expression level was significantly higher than that in other types of soft tissue sarcomas such as pleomorphic liposarcoma (PLS) and leiomyosarcoma (LMS)." (PMID 37228502, 2023).
pleural mesothelioma (1 paper, 2023). A neoplasm that arises from the mesothelial cells of the pleura. "In the current study, we further explored the role of FGF18 in pleural mesothelioma and evaluated its suitability as a blood‐based biomarker." (PMID 37340889, 2023). "We analyzed circulating FGF18 in the plasma of 40 patients with pleural mesothelioma, six patients with pleural fibrosis and 40 healthy controls." (PMID 37340889, 2023). "FGF18 was significantly decreased in the plasma of patients with pleural mesothelioma and pleural fibrosis compared with healthy controls." (PMID 37340889, 2023). "Within the pleural mesothelioma cohort, FGF18 was not significantly correlated with overall survival or other disease parameters." (PMID 37340889, 2023).
renal cell carcinoma (1 paper, 2018). "In renal cell carcinoma, down-regulation of CXXC4 by siRNA resulted in the up-regulation of some cellular proliferation related genes (FGF18, EGR1, and MYCN), the down-regulation of apoptosis inhibitor proteins BIRC7 and XAF1, and some other important tumor progression factors." (PMID 30042169, 2018).
Sepsis (1 paper, 2024). Sepsis is defined as life-threatening organ dysfunction caused by a dysregulated host response to infection. "This study enriched the regulatory mechanism of NF-κB in sepsis-associated ALI, suggesting that FGF18 may be a therapeutic pathway for ALI." (PMID 38419044, 2024).
serous ovarian tumors (1 paper, 2016). "Furthermore, a recent study provides a platform for the identification of blood-based biomarkers (“Secretome”) for high-grade, advanced-stage serous ovarian tumors and identifies two new markers, FGF18 and GPR172." (PMID 27259239, 2016).
Stroke (1 paper, 2025). Sudden impairment of blood flow to a part of the brain due to occlusion or rupture of an artery to the brain. "In an in vivo study, FGF18 was found to be effective in reducing infarct volume and ameliorating behavioral deficits in the stroke model." (PMID 39787159, 2025).
synovial sarcoma (1 paper, 2023). "Stimulation of human synovial sarcoma cell line HS-SY-II with recombinant FGF18 protein increased the dependence of the cells on FGF18 and enhanced the phosphorylation levels of ERK, P38 and FGFR3 proteins in human synovial sarcoma cell line HS-SY-II." (PMID 37228502, 2023). "Thus, exogenous FGF18 promotes synovial sarcoma growth through FGFR3 and ERK pathways in synovial sarcoma cell lines." (PMID 37228502, 2023).
testicular cancer (1 paper, 2020). A primary or metastatic malignant neoplasm that affects the testis. "Here, from the microarray analysis of cordycepin-mediated alteration of gene expression levels in testicular cancer cells, the clustering of the microarray data identified that the mRNA level of FGF9 and FGF18 were reduced in 100 μg/mL cordycepin-treated MA-10 cells." (PMID 33172093, 2020).
viral infection (1 paper, 2024). "FGF18 expression was significantly increased in VSV-infected hosts, suggesting that viral infection influences cell fate." (PMID 38225547, 2024).